SOST (sclerostin)
Diseases named in the same sentence as SOST in open-access papers (continued):
Sharing a sentence is not in itself a finding about the gene and the disease.
type 2 diabetes (60 papers, 2014 to 2026). "We report on genetic evidence supporting that lower sclerostin levels are causally related with both coronary artery disease and type 2 diabetes." (PMID 39537602, 2024). "A sclerostin-neutralizing antibody reverses bone loss, mitigates inflammation, and partially restores periodontal ligaments in a preclinical model of type 2 diabetes-induced periodontal disease." (PMID 39171525, 2024). "For example, one study revealed that a reduction in sclerostin levels was associated with an increased risk of MI, type 2 diabetes, and coronary artery calcification, whereas lower sclerostin levels were correlated with a higher risk of MI and hypertension." (PMID 39767786, 2024). "Here, authors show that lower sclerostin levels are associated with a higher risk of coronary artery disease, type 2 diabetes, and adverse cardiovascular biomarkers across the lifespan." (PMID 39537602, 2024). "Concordant findings were seen in two studies, comprising an effect of sclerostin lowering on increased risk of MI and type II diabetes mellitus." (PMID 37490188, 2023). "In this study, it was aimed to check the association of sclerostin with insulin resistance/sensitivity, and β-cell function in healthy, prediabetes, and type 2 diabetic patients." (PMID 36004027, 2022). "It was reported that the blood sclerostin level can become reliable diagnostic and prognostic biomarker of cardiovascular risk in patients with type 2 diabetes." (PMID 35216490, 2022). "Diet-induced weight loss in type 2 diabetes was reported to induce significant increases in born turnover and serum sclerostin levels." (PMID 34572220, 2021). "In addition, the blood level of sclerostin is positively associated with the carotid-femoral pulse wave velocity (cfPWV) and independently predicts aortic stiffness in patients with type 2 diabetes." (PMID 35216490, 2022). "Furthermore, in type 2 diabetes patients, there is an association between the presence of atherosclerotic disease and serum sclerostin levels." (PMID 32366042, 2020). "However, genetically predicted lower sclerostin levels led to 25–85% excess coronary artery disease risk, 40% to 60% increased risk of type 2 diabetes, and worse cardiovascular biomarkers values, including higher triglycerides, and decreased HDL cholesterol levels." (PMID 39537602, 2024). "Therefore, this study aims to evaluate whether six bone markers (osteocalcin, osteopontin, osteonectin, osteoprotegerin, alkaline phosphatase, sclerostin) are associated with CVD risk in patients with type 2 diabetes." (PMID 29571288, 2018). "Sclerostin is also associated with the duration of type 2 diabetes mellitus (T2DM) and the level of glycated hemoglobin (HbA1c) in T2DM patients." (PMID 25276128, 2014). "Sclerostin levels are elevated in both type 1 and type 2 diabetes due to a combination of metabolic and vascular factors." (PMID 40731833, 2025). "Analyses of the samples, using a technique called real-time-PCR, revealed that gene expression of sclerostin was increased in samples of type 2 diabetes patients, which led to a downregulation of Wnt signaling related genes." (PMID 38598270, 2024). "Type 2 diabetes (T2D) is associated with an increased risk of cardiovascular disease (CVD) and increased serum and tissue expression of sclerostin." (PMID 37919715, 2023). "HbA1c shows a significant correlation with sclerostin in prediabetes and newly diagnosed type 2 diabetes." (PMID 36004027, 2022). "We found significantly higher circulating sclerostin levels in the newly diagnosed type 2 diabetes male individuals compared to the healthy male control group and it was corroborating with SOST mRNA expression." (PMID 36004027, 2022). "In an adult study, serum sclerostin level increased in patients with type 2 diabetes compared to healthy controls and showed a positive correlation with body mass index (BMI) and fat mass." (PMID 34572220, 2021).
type 2 diabetes (continued). "The roles of sclerostin appear to be complicated: It exerts pro-adiposity and pro-insulin resistance effects in type 2 diabetes and has an anti-calcification effect during cardiovascular disease." (PMID 32544571, 2020). "A direct relationship between sclerostin and insulin resistance has been found in obese patients and patients with type 2 diabetes." (PMID 32503328, 2020). "We followed up a cohort of 130 participants (mean age 56.8 years; 48.5% females; 75 with type 2 diabetes; 46 with prevalent cardiovascular disease) in which serum sclerostin levels were measured at the baseline." (PMID 29928063, 2018). "This cross-sectional study found that circulating sclerostin level was significantly higher in type 2 diabetic patients with CKD-G3 or G4/5 stage than those with G1/2 stage." (PMID 25053944, 2014). "In the present study, we assessed serum sclerostin level according to renal function in patients with type 2 diabetes." (PMID 25053944, 2014). "A recently published study proved a causal relationship between reduced sclerostin (SOST variants: rs7220711 and rs66838809) and an increased risk of coronary artery disease (OR = 1.85 [1.12, 3.06]) and type 2 diabetes (OR = 1.35 [0.98, 1.87] by Mendelian randomization (MR) analysis." (PMID 40429697, 2025). "Similarly, in patients with type 2 diabetes, elevated sclerostin levels were demonstrated to be correlated with increased carotid intima-media thickness (cIMT), potentially as a protective mechanism to slow the progression of atherosclerosis." (PMID 39767786, 2024). "Patients with both type 1 diabetes and type 2 diabetes have high levels of serum sclerostin." (PMID 39720253, 2024). "This study detailed whether the alteration of sclerostin gene expression and of accumulation of advanced glycation end-product (AGE) can affect bone turnover and fracture risk in patients with type 2 diabetes (T2D)." (PMID 35506206, 2022). "How the association between PTH and insulin resistance relates to a reduced bone turnover in patients with type 2 diabetes is not well understood, but a possible mechanism may be elicited by osteocytic dysfunction with excess production of sclerostin." (PMID 35422766, 2022). "Increased serum sclerostin levels have been reported in both type 1 and type 2 diabetes patients." (PMID 34690653, 2021). "This suggests that the increased level of sclerostin might be used as a marker of decreased bone formation in premenopausal women with type 2 diabetes." (PMID 34690653, 2021). "In a mixed population of people with and without type 2 diabetes, serum sclerostin was positively associated with the presence of aortic calcifications and cardiovascular mortality over the eight-year longitudinal study." (PMID 33776907, 2021). "Accumulation of mineralized matrix might induce expression of sclerostin, described to be increased in type 2 diabetics, by osteocytes, thus, actively inhibiting maturation of the osteogenic precursor cells by inhibiting Wnt signaling." (PMID 33805833, 2021). "But the cohort study performed among 1778 subjects without a history of type 2 diabetes did not confirm the association between sclerostin levels and risk of type 2 diabetes." (PMID 32592042, 2020). "Genetically predicted lower levels of sclerostin were associated with lower levels of HDL cholesterol, with beta = −0.15 [−0.2, −0.09], higher odds of coronary artery disease, with OR = 1.25 [1.01, 1.55] and higher odds of type 2 diabetes, with OR = 1.45 [1.11, 1.90]." (PMID 39537602, 2024). "However, it is not currently clear whether renal dysfunction has an effect on circulating sclerostin level in patients with type 2 diabetes." (PMID 25053944, 2014). "A lot of studies have also been conducted on the expression of sclerostin in type 2 diabetes (T2D)." (PMID 39720253, 2024).
type 2 diabetes (continued). "Other studies have reported a positive correlation between sclerostin levels and the homeostasis model assessment of insulin resistance (HOMA–IR) in prediabetic adults and those with type 2 diabetes." (PMID 34572220, 2021). "Exendin-4 was found to reduce the serum levels of sclerostin, increase the levels of osteocalcin, and increase the femoral BMD in a type 2 diabetic animal model." (PMID 27997588, 2016). "Age and smoking status affected the balance of DKK1 and SOST, while type 2 diabetes and sex did not demonstrate a significant influence." (PMID 38499638, 2024). "Men and women with type 2 diabetes have significantly higher serum sclerostin than non-diabetic controls." (PMID 33776907, 2021). "The current study aimed to evaluate the relationship between circulating sclerostin levels and cardiovascular and non-cardiovascular mortality in individuals with and without type 2 diabetes." (PMID 29928063, 2018). "This study did not detect an association between sclerostin and CVD incidence in patients with type 2 diabetes; however, additional research is necessary to confirm this null result." (PMID 29571288, 2018). "The present study aimed to assess the serum levels of SOST and irisin in Egyptian type 2 diabetic (T2DM) female patients with and without atherosclerosis and explore the possible relationship between both markers and other studied parameters among the studied cohorts." (PMID 30403705, 2018). "In a cross-sectional study, serum sclerostin levels in patients with type 2 diabetes mellitus (T2DM) were significantly higher than those without T2DM." (PMID 37199584, 2023). "Indeed, a case control study was conducted to detect the levels of sclerostin in Egyptian female patients with type 2 diabetes with and without atherosclerosis, they found a positive relationship between sclerostin and atherosclerosis in patients with type 2 diabetes." (PMID 35546224, 2022).
myeloma (47 papers, 2012 to 2025). "Recently, the gene encoding sclerostin has been shown to be expressed in patients with multiple myeloma, which is associated with the pathogenesis and prognosis of the disease." (PMID 39747949, 2025). "Sclerostin is involved in bone loss associated with multiple myeloma and bone cancers and possibly involved in their pathogenesis." (PMID 35563281, 2022). "For example, expression of osteocytic proteins that are associated with multiple myeloma bone metastasis, such as sclerostin, are associated with mature osteocytes." (PMID 30034365, 2018). "Treatment of the myeloma-bearing mice in all three cell lines with an anti-sclerostin antibody caused an increase in osteoblastogenesis, reduced the development of osteolytic lesions and prevented myeloma-induced bone loss whilst increasing bone strength." (PMID 29098361, 2018). "In addition, we examined the association of myeloma cell expression of TP with RANKL or sclerostin levels in myeloma patients and found a positive correlation." (PMID 35760800, 2022). "In pre-clinical mouse models anti-sclerostin antibodies prevented bone loss and increased fracture resistance, which was further enhanced by combining with zoledronate, making Romosozumab an attractive treatment for myeloma bone disease." (PMID 36072809, 2022). "BPS804, another anti-sclerostin fully humanized mAb that has received orphan drug status for the treatment of osteogenesis imperfecta, has demonstrated the ability to reduce myeloma-induced bone loss in preclinical studies although human trials of BPS804 in MM patients have yet to be initiated." (PMID 30544512, 2018). "They found higher levels of sclerostin in patients with newly diagnosed multiple myeloma compared to controls (mean: 0.48 ng/ml vs. 0.31 ng/ml; p = 0.01)." (PMID 39747949, 2025). "All these studies have turned sclerostin into an emerging target for treating myeloma-induced lytic bone disease and prompted the investigation of sclerostin antibodies in a clinical trial with multiple myeloma patients (NCT05775094)." (PMID 37174109, 2023). "Preclinical animal studies showed that anti-sclerostin antibodies induce new bone formation in bones infiltrated with myeloma or breast cancer cells, increase bone mass, and improve bone mechanical properties." (PMID 37174109, 2023). "Future research trends in this area include safety and targeting studies on sclerostin antibodies, potential target drugs for multiple myeloma (MM), and high-quality clinical trials for the treatment of osteoarthritis (OA)." (PMID 38033331, 2023). "As discussed in Section 5, 2DDR production by myeloma cells and the consequent activation of CIITA in osteocytes are also partially responsible for the elevated SOST, the gene encoding sclerostin, expression in bones bearing myeloma tumors." (PMID 37174109, 2023). "We aimed to examine the serum DKK-1 and sclerostin variations in newly diagnosed multiple myeloma (NDMM) patients at diagnosis and in the course of therapy, including autologous stem cell transplantation (ASCT)." (PMID 37445475, 2023). "Current and developing research hotspots focus on bone mass, sclerostin antibody, multiple myeloma, and cartilage development." (PMID 38033331, 2023). "In vitro, pharmacological inhibition of DKK-1 prevented sclerostin upregulation by myeloma cells, and treatment with recombinant DKK-1 increased it." (PMID 37174109, 2023). "This suggests that osteocyte-derived sclerostin contributes to the profound suppression of osteoblasts by myeloma cells." (PMID 37174109, 2023). "In vitro, co-culture with myeloma cells increases SOST/sclerostin in osteocyte cell lines and authentic osteocytes." (PMID 37174109, 2023). "Inhibition of sclerostin expression significantly reduces osteolytic bone lesions in a mouse model of myeloma." (PMID 37860014, 2023). "Collectively, our results demonstrate the mechanism by which myeloma cells upregulate osteocyte derived RANKL and sclerostin in myeloma." (PMID 35760800, 2022).
myeloma (continued). "Further studies are needed to clarify the mechanisms by which ectopic expression of sclerostin occurs in multiple myeloma and bone metastasis of breast cancers." (PMID 35563281, 2022). "Circulating serum RANKL and sclerostin are significantly elevated in patients with multiple myeloma and are correlated with the status of lytic lesions in patients." (PMID 35760800, 2022). "Expressed by mature osteocytes, fibroblast like synovial cells, and even myeloma cells directly, sclerostin functions as a key regulator of the canonical Wnt/βcatenin pathway." (PMID 36550970, 2022). "Multiple myeloma cells reportedly stimulated the expression of sclerostin in osteoblasts through Dkk1." (PMID 35563281, 2022). "Sclerostin also secreted from myeloma cells and inhibited the differentiation of human bone marrow stroma cells into osteoblasts in cultures." (PMID 35563281, 2022). "Attempts to therapeutically target RANKL and sclerostin in myeloma patients have been used to treat bone destruction." (PMID 35760800, 2022). "SOST is expressed by both myeloma cells and osteocytes, and it acts as a negative regulator of the Wnt pathway and, consequently, bone formation." (PMID 35681747, 2022). "Regarding SOST, it is expressed by osteocytes and myeloma cells and it is a negative regulator of the Wnt pathway and bone formation." (PMID 33809268, 2021). "During the progression of multiple myeloma, osteocytes directly interact with multiple myeloma cells, which stimulate osteocytes to produce sclerostin and RANKL." (PMID 33162934, 2020). "Multiple myeloma, a cancer that directly affects bone, induces osteocyte apoptosis and osteocyte-derived sclerostin and RANKL expression." (PMID 32733380, 2020). "Wnt inhibitors Dkk1 and sclerostin are elevated in the serum and bone marrow of patients with myeloma, and blocking their action improves myeloma bone disease pre-clinically." (PMID 31586071, 2019). "Serum sclerostin concentration is elevated in patients with multiple myeloma and bone lesions, while a correlation with bone destruction has been suggested." (PMID 31698687, 2019). "Impaired osteoblast differentiation in myeloma has previously been attributed to excessive Wnt inhibition, with particular implication of Wnt inhibitors Dkk1 and sclerostin." (PMID 31586071, 2019). "Serum and bone marrow sclerostin concentrations are significantly higher in patients with multiple myeloma than in healthy subjects or leukemia patients." (PMID 31698687, 2019). "In preclinical mouse models of multiple myeloma, treatment with blocking anti-sclerostin antibody increased osteoblast numbers and bone formation rate reducing osteolytic bone lesions." (PMID 30410490, 2018). "Nevertheless, the combination therapy of anti-sclerostin antibody and the proteasome inhibitor carfilzomib, displayed potent anti-myeloma activity as well as positive effects on bone disease in vivo." (PMID 30410490, 2018). "A recent study of myeloma cell lines and patient samples concluded that osteocytes, rather than malignant plasma cells, appear to be the source of sclerostin." (PMID 30544512, 2018). "Recent studies have revealed a vital role of sclerostin in multiple myeloma with osteolytic bone lesions." (PMID 28900298, 2017). "Our results showed that SOST is expressed significantly in primary myelomacells derived from MM patients and myeloma cell lines." (PMID 24027669, 2013). "Expression of sclerostin in human myeloma cellline (U266) was evaluated as myeloma cells withmyeloma markers (CD38+, CD138+, CD19-) andT293 and K562 as negative control." (PMID 24027669, 2013). "Intriguingly, sclerostin has also been found to be expressed by malignant plasma cells in multiple myeloma." (PMID 23717504, 2013). "Increased secretion of sclerostin by myeloma cells has been shown to inhibit osteoblast function." (PMID 39747949, 2025). "Myeloma cells are known to produce and shed sclerostin into the serum/plasma of patients." (PMID 38247829, 2024).